UGT1A1 (UDP glucuronosyltransferase family 1 member A1)
Diseases named in the same sentence as UGT1A1 in open-access papers (continued):
Sharing a sentence is not in itself a finding about the gene and the disease.
cancer (continued). "Recent literature elucidating the roles of oncogenes and predictive biomarkers on anti-cancer drugs and UGT1A1 genotypes are described." (PMID 40432911, 2025). "In this in-depth study, we systematically analyzed the impact of UGT1A1*6 and UGT1A1*28 polymorphisms on the efficacy and toxicity of irinotecan (IRI) chemotherapy in Chinese cancer patients." (PMID 40170723, 2025). "By understanding how UGT1A1 contributes to cancer resistance, we can develop new strategies to overcome it." (PMID 40432911, 2025). "Irinotecan, methotrexate, cyclosporine A, and rifampicin share similar UGT1A1 inhibitory activity in the treatment of cancer." (PMID 40291905, 2025). "Given the dual role of ABCG2 and UGT1A1 on efflux and metabolism of the active metabolite of irinotecan, SN-38, we have investigated the potential of SCO-101 to inhibit both ABCG2 and UGT1A1 activity and reverse drug resistance in cancer models." (PMID 40332396, 2025). "This section explores the pharmacogenomics of UGT1A1, with a particular emphasis on its clinical relevance in irinotecan-based cancer therapies." (PMID 40149251, 2025). "This review highlights the impact of key genes, such as CYP2D6, DPYD, and UGT1A1, which influence the metabolism of essential cancer drugs like tamoxifen, fluoropyrimidines, and irinotecan." (PMID 40149251, 2025). "We present data on cancer chemotherapy-related pharmacogene variant frequencies in DPYD, UGT1A1, TPMT, NUDT15, and ABCB1 within the Chilean population, offering insights for the strategic implementation of pharmacogenetic testing." (PMID 38675222, 2024). "This research program intends to support the large-scale feasibility, safety and cost-effectiveness of upfront DPYD (and eventually UGT1A1) genotyping for people in Australia affected by cancer." (PMID 39516829, 2024). "The described studies indicated that some components of fruits and vegetables might increase UGT1A1 activity in individuals with the 7/7 genotype variant, which is most common in GS, thereby potentially improving the clearance of certain carcinogens from the body and reducing cancer risk." (PMID 39064690, 2024). "The study included cancer patients homozygous or heterozygous for UGT1A1*28 or UGT1A1*6 originally excluded in the phase 1 trial." (PMID 39204392, 2024). "The objective of the retrospective analysis of these RWD was to demonstrate the feasibility of the DPYD and UGT1A1 pharmacogenetic testing prior to starting chemotherapy in these patients, specifically for community‐based cancer centers." (PMID 38752299, 2024). "Other cancer types also showed a higher prevalence of UGT1A1*60 (NSCLC, 43.2%, p = 0.004; CRC, 55.0%, p = 0.001) than in normal groups, which were different from other Asian populations (28.0%–34.0%, p = 0.106)." (PMID 36239106, 2022). "This study leverages implementation science frameworks to evaluate the implementation of DPYD and UGT1A1 testing, while developing infrastructure for genomic medicine in our cancer centers to ensure sustainability of PGx testing as standard of care." (PMID 35865463, 2022). "Samples from cancer patients (n = 701) already tested using PCR and electrophoresis prior to treatment with irinotecan for rs34983651 (UGT1A1*28) in a Spanish hospital were genotyped for rs887829 (UGT1A1*80) using real-time PCR with a TaqMan probe." (PMID 36297516, 2022). "We compared methods for and the results of genotyping UGT1A1*80 in a population of cancer patients previously tested for UGT1A1*28 prior to selection of treatment in daily clinical practice." (PMID 36297516, 2022). "Korean cancer patients appeared to have similar frequency patterns of the UGT1A genotype irrespectively of cancer type and appeared to have a higher prevalence of UGT1A1*6 and UGT1A1*60 than normal Koreans." (PMID 36239106, 2022). "This study has some limitations, first, a potentially under-powered sample size for the non-UGT1A1 instruments to detect small effects in some cancers." (PMID 33671849, 2021).
cancer (continued). "A population PK/PD model accommodating PGx information was created to predict the occurrence of myelosuppression in cancer patients carrying different genotypes of UGT1A1 following different dosing strategies of irinotecan." (PMID 33733372, 2021). "Established resources for pharmacogenetic guidance were identified, and recommendations were evaluated for UGT1A1-guided therapy for irinotecan, belinostat, pazopanib, or nilotinib to elucidate further the role of UGT1A1 in guiding cancer pharmacotherapy." (PMID 33805415, 2021). "The extent of compiled evidence mainly in adults treated for various kinds of cancers for association of IRT and UGT1A1 persuaded several regulatory bodies including the FDA to issue a warning for UGT1A1*28 poor metabolizers." (PMID 27618021, 2016). "A previous meta-analysis of 12 studies (8 studies were included in our meta-analysis) was performed to analyze the difference in TR between IRI-administered cancer patients with different UGT1A1*28 genotypes." (PMID 23516488, 2013). "Among them, Cd34, protein tyrosine phosphatase, receptor type, F (Ptprf), Txnrd1, Pgd, Ugt1a1, Gpr137b, and dynein light chain Tctex-type 1 (Dynlt1) were connected in a molecular network of cancer-cell cycle-cell death." (PMID 22039513, 2011). "Hence, these data highlight an interesting dual mechanism of action for SCO-101 as inhibitor, also contributing to overcoming the difficulty in developing UGT inhibitors with low toxicity and underscoring the relevance of targeting UGT1A1 in cancer as well." (PMID 40332396, 2025). "Some studies have suggested that UGT1A1*6 or UGT1A1*27 might be more important among Asian cancer patients treated with irinotecan." (PMID 36239106, 2022). "Kaplan–Meier plots and logrank tests revealed that six UGT genes were significantly associated with increased overall survival (OS) rates [UGT1A1 (LUSC), UGT1A6 (ACC), UGT1A7 (ACC), UGT2A3 (KIRC), UGT2B15 (BLCA, SKCM)] or decreased OS rates [UGT2B15 (LGG), UGT8 (UVM)] in specific cancers." (PMID 34503303, 2021). "However, clinical guidance for integrating UGT1A1 results into cancer care are sparse and can be inconsistent." (PMID 33805415, 2021). "Among them, the UGT1A gene family (including UGT1A1 and UGT1A3–UGT1A10) has important roles in pharmacology and toxicology, contributing to interindividual differences in drug disposition and cancer risk." (PMID 34595239, 2021). "The detection of c.211G > A (p.Gly71Arg) pathogenic variant in UGT1A1 gene in patients 3/III‐1 and 3/III‐2 suggested that this mutation might have triggered the occurrence of cancer by affecting the retinoic acid metabolism in patients." (PMID 31207142, 2019). "UGT1A1 is also the only enzyme which catalyzes the glucuronidation of the potent antioxidant bilirubin, which may play a protective role against cancer." (PMID 26751466, 2016). "The authors suggested that the determination of the UGT1A1 genotypes might be clinically useful for predicting severe toxicity by irinotecan in cancer patients." (PMID 15280927, 2004). "UGT1A1 may play a role in the development of resistance to cancer drugs." (PMID 40432911, 2025). "Overall, these observations support the use of SCO-101 as a safe clinical candidate for cancer patients, in combination with ABCG2 and UGT1A1 substrates." (PMID 40332396, 2025). "UGT1A1 protein and OGDHL, a component of the OGDC enzyme complex and a key control point in the citric acid cycle often bypassed in cancer cells." (PMID 36295907, 2022). "Intriguingly, van Erp and co-authors (2005) investigated the effects of milk thistle extract (200 mg containing 80% silymarin, thrice daily) in six cancer patients on the pharmacokinetics of irinotecan, substrate for CYP3A4 and UGT1A1." (PMID 32635538, 2020).
cancer (continued). "UGT1A1*28 is a member of family in SNPs of UGT1A1 gene, previous meta-analysis evaluated the impact of UGT1A1*28 polymorphisms with IRI-induced toxicity, and demonstrated UGT1A1*28 polymorphisms may be considered as a marker of IRI-induced toxicity in chemotherapy of cancer." (PMID 32936306, 2020). "Five core ADME genes coding for phase II drug metabolism enzymes showed significant associations of their intratumoral expression levels with OS rates in cancers, including GSTP1, NAT1, UGT1A1, UGT2B15, UGT2B7." (PMID 33202946, 2020). "UGT1A1 and UGT1A9 enzymes metabolize SN-38, the active form of the cancer drug irinotecan." (PMID 40432911, 2025). "For example, cancer drugs with actionable drug-gene pairs (e.g., CYP2D6-tamoxifen, DPYD-fluoroucil, DPYD-tegafur, UGT1A1-irinotecan, DPYD-capecitabine) could be considered." (PMID 40894378, 2025). "In a literature review conducted between 1984 and 2013, global variations in the UGT1A1 gene were analyzed in a sample of 146 Lebanese without cancer and compared to other populations." (PMID 40432911, 2025). "This implies that estrogen-related mechanisms may affect the two cancers differently, although some genomic regions, including COMT, ESR1, and UGT1A1, impact both the risks of female DGC and OvC." (PMID 39862296, 2025). "Secondly, there is no recommendation on UGT1A1*80 genotyping to avoid irinotecan-induced toxicity in cancer patients." (PMID 36297516, 2022). "This high interindividual variable expression for UGT1A1 and other UGT genes may result in intratumoral variabilities in the conjugation of UGT substrates and hence impact cancer progression and patient survival as assessed in Section 3.4." (PMID 34503303, 2021). "In Japanese cancer patients, UGT1A1*28, UGT1A9*1b, UGT1A1*6 (211G > A), and UGT1A1*60 (3279 T > G) are closely associated with the UGT1A9 IVS1 + 399 (I399C > T) polymorphism, and linkage of I399C > T with these variants has been shown to affect irinotecan metabolism." (PMID 24650752, 2014). "Interestingly, both the phase II genes (UGT1A1 and TPMT) predominantly affect drugs for cancer." (PMID 38535119, 2024). "The inter-individual variation in enzyme activity of UGT1A1 isozyme due to the polymorphisms at positions −3156 (G > A), 211 (G/A) and TATA Box (6TAA/7TAA) leads to the lack of bilirubin and the development of cancer." (PMID 28056823, 2017). "In addition, irinotecan or its active metabolite is administered in different pharmaceutical forms, in monotherapy or combined with other drugs in different therapeutic regimens, at different doses regardless of the patient’s UGT1A1 genotype, and in the treatment of different cancer streams." (PMID 40430836, 2025).
tumor (61 papers, 2005 to 2025). "Chemical accumulation from UGT1A1 dysfunction promotes DNA damage and tumor risk, while genetic variations in UGT1A1 can affect GC risk via modifying the enzyme’s chemical elimination." (PMID 41031088, 2025). "Zhai and colleagues reported PK and UGT1A1 polymorphism data in 49 patients with refractory neoplasms treated with 1-hour IV flavopiridol." (PMID 21072184, 2010). "The group of SULT1A1*1/*1 and UGT1A1*1/*1, UGT1A1*1/*33 and UGT1A1*33/*33 high-activity genotypes was associated with tumor size ≤2 cm (OR = 9.02, CI = 1.59–51.31, P = 0.01) and low tumor grade (OR = 10, CI = 1.09–100, P = 0.04)." (PMID 16280036, 2005). "Interestingly, the toxicity and tumor response to FOLFIRI also correlate with UGT1A variants—UGT1A1, UGT1A7, and UGT1A9—and haplotypes including these variants." (PMID 36308049, 2023). "Polymorphisms of the UGT1A1 gene have also displayed an association with tumor response." (PMID 33985435, 2021). "In this study, we assessed whether the chemo-susceptibility of LACC could be evaluated based on tumor expression microarray analysis and host UGT1A1 genotyping, in order to optimize the efficacy of NAC-RH." (PMID 26482555, 2015). "We considered that the UGT1A1 genotypes of cancerous tissues matched those of the host, although there has been no report to date on the correlation of UGT1A1 polymorphisms between the tumor and host." (PMID 26482555, 2015). "The results showed that the addition of Irinotecan, guided by the UGT1A1 genotype, to Capecitabine-based neoadjuvant chemoradiotherapy led to a significant increase in complete tumor response among Chinese patients." (PMID 40432911, 2025). "The clinical value of UGT1A1 genotyping lies in reducing drug-related adverse reactions while preserving tumor response rates and minimizing morbidity/mortality." (PMID 40432911, 2025). "The UGT1A1/3/8/9/10 expression level is positively correlated with the activity of tumor-infiltrating immune cells, particularly B cells." (PMID 37056387, 2023). "It suggested no significant survival benefit but revealed a positive effect on tumor response in patients with the UGT1A1 PM phenotype." (PMID 35267552, 2022). "Six (15%) patients (UGT1A1 wild‐type [n = 2] and heterozygous [n = 4]) showed objective responses, including partial response (n = 1), tumor shrinkage (n = 4), and improved findings on their MIBG scan (n = 1)." (PMID 35233973, 2022). "In total, six (15%) patients (UGT1A1 wild‐type [n = 2] and heterozygous [n = 4]) showed an OR, including PR (n = 1), tumor shrinkage (n = 4), and improved findings on the MIBG scan (n = 1)." (PMID 35233973, 2022). "The proportion of female patients, as well as patients with poor ECOG PS, tumor location at the pancreas head, UGT1A1 IM, UGT1A1 PM, high platelet count, and total bilirubin level, was significantly higher in the FN group than in the non-FN group." (PMID 35267552, 2022). "The expression of UGT1A1, UGT1A6, and UGT1A10 increased as the tumor progressed, suggesting that the UGT1A gene family plays an important role in the tumorigenesis and progression of PC." (PMID 34595239, 2021). "Adding irinotecan guided by UGT1A1 genotype to capecitabine-based neoadjuvant chemoradiotherapy significantly increased complete tumor response in Chinese patients." (PMID 33119477, 2020). "UGT1A1 was shown in the nucleus, cytoplasm, and cell surface of para-tumor tissue at a low expression level." (PMID 32983995, 2020). "We found that UGT1A1 was expressed in the nucleus, cytoplasm, and cell surface in para-tumor tissues at a low expression level." (PMID 32983995, 2020).
tumor (continued). "And subsequently, the mRNA expression level of UGT1A1 was also significantly down-regulated in three of five HBV-positive HCC tumor tissues (P < 0.05), while individual differences were also observed in P2-07271 and P4-A11101." (PMID 26010150, 2015). "Comparing with the adjacent normal HLMs, the basis protein expression level of UGT1A1 was also decreased in three of five tumor HLMs (P < 0.01)." (PMID 26010150, 2015). "Although several meta-analyses have examined the correlation between UGT1A1 genotype and the efficacy of irinotecan-based regimens, including tumour response and survival, their results remain controversial." (PMID 25880011, 2015). "While the association between UGT1A1*28 and IRI-related toxicity has been extensively studied, data are limited regarding the potential impact of the UGT1A1*28 genotype on tumor responsiveness and patient survival following IRI therapy." (PMID 23516488, 2013). "Associations between UGT1A1 (TA)n, UGT1A1 –3156G>A, SLCO1B1*1b 388A>G and ABCC1 IVS11 –48C>T genotypes and drug response (tumour DS, ypT0, OS and RFS) to 5-FU+irinotecan were evaluated for the 35 patients of group 2." (PMID 22045187, 2011). "The Cox regression model included the UGT1A1 genotype, ECOG, sex, age, clinical-risk EORTC classification and primary tumour localisation." (PMID 21654688, 2011). "Our data confirm the role of UGT1A1*28 variant as the most important in taking a decision and, for the first time, reveals TYMS 5′TRP polymorphism to be strongly related with tumour response in these patients." (PMID 20628391, 2010). "A recent evidence-based review described the proposed clinical utility of UGT1A1 genotyping, as three recent studies they reviewed found statistically significant higher tumour response rates among individuals homozygous for a particular allele." (PMID 19338662, 2009). "Individuals with both SULT1A1 and UGT1A1 high-activity genotypes had low tumor grade (odds ratio = 2.56, 95% confidence interval = 1.04–6.25, P = 0.05)." (PMID 16280036, 2005). "Individuals who carried genotypes predicting both high-activity SULT1A1*1/*1 and high-activity UGT1A1*1/*1, UGT1A1*1/*33 and UGT1A1*33/*33 presented with low tumor grade (grade 1) (OR = 2.56, CI = 1.04–6.25, P = 0.05)." (PMID 16280036, 2005). "In the multivariate analysis, female sex (OR, 2.87; p = 0.021), ECOG PS = 1 (OR, 3.86; p = 0.015), tumor location of the pancreatic head (OR, 3.06; p = 0.023), UGT1A1 IM group (OR, 4.78; p = 0.005), and UGT1A1 PM group (OR, 4.86; p = 0.035) were independently associated with FN." (PMID 35267552, 2022). "Importantly, our results also showed that the expression levels of UGT1A1/3/8/9/10 were positively correlated with the activities of tumor-infiltrating immune cells, especially B cells." (PMID 34595239, 2021). "Furthermore, the expression levels of UGT1A1/3/8/9/10 were positively correlated with the activities of tumor-infiltrating immune cells, especially B cells." (PMID 34595239, 2021). "Then, the upregulation of UGT1A1 mRNA was found in the tumor of patients with TNBC." (PMID 32983995, 2020). "Moreover, it indicated overexpression of UGT1A1 in TNBC tumor tissues compared with para-tumor tissues." (PMID 32983995, 2020). "Our results further indicated a high UGT1A1 expression level in TNBC tumor tissues." (PMID 32983995, 2020). "However, the expression of UGT1A1 in tissues of patients with TNBC was much more than the matched para-tumor tissues." (PMID 32983995, 2020). "The results indicated high level of UGT1A1 expression in tumor tissue of patient with TNBC." (PMID 32983995, 2020). "Interestingly, the toxicity and tumor response of concurrent leucovorin, 5-fluorouracil, and irinotecan (FOLFIRI) reportedly also correlate with UGT1A variants (UGT1A1, UGT1A7 and UGT1A9) and haplotypes including these variants." (PMID 25175642, 2014). "We also compared the expression levels of UGT1A1 mRNA to tumor stage." (PMID 30349745, 2012).